ASCL1 (achaete-scute family bHLH transcription factor 1)
Diseases named in the same sentence as ASCL1 in open-access papers (continued):
Sharing a sentence is not in itself a finding about the gene and the disease.
tumor (continued). "This migration difference could be due in part to the manner of tumor induction and/or tumor cell-of-origin, or possibly due to the low levels of Ascl1 in these adult OPC-induced Olig2-CKO tumors, as revealed by bulk RNA-seq33." (PMID 39609428, 2024). "Consistent to our hypothesis, MYC amplification promoted tumor development with low Ascl1 expression though in SCLC mouse models." (PMID 38233864, 2024). "However, despite this similarity, the immunofluorescent levels of ASCL1 in Olig2-CKO tumor cells were slightly lower than control and significantly lower compared to Ascl1-OE tumor cells." (PMID 39609428, 2024). "We hypothesized that if ASCL1 is required to promote tumor migration, then increasing the levels of ASCL1 should overcome the repression by OLIG2, resulting in a highly migratory and diffuse tumor phenotype similar to Olig2-CKO tumors." (PMID 39609428, 2024). "Indeed, the migration distance of Ascl1-OE GFP+ tumor cells on the contralateral corpus callosum was similar to that of Olig2-CKO tumors." (PMID 39609428, 2024). "All three subtypes were represented within both tumor models, with the proneural subtype expanded almost 2-fold (44%) in Ascl1-OE tumors at the expense of the classical subtype (31%) compared to control tumors (25% proneural, 45% classical), while the mesenchymal subtype was mostly unaffected." (PMID 39609428, 2024). "As there were no NEPC–N tumors represented in our TMA cohort, which consists of punch biopsies from tumor blocks, we further studied full face sections of a liver metastasis from a patient with ASCL1–positive NEPC, a case previously identified in a study of neuroendocrine chromatin landscapes." (PMID 38645034, 2024). "Moreover, tumour-associated CD8 + T cells are interconnected with molecular subtype; the non-ASCL1/NEUROD1 subtypes have significantly more CD8 + T cells than those of the ASCL1/NEUROD1 subtypes, thus they can benefit more from immunotherapy." (PMID 37870696, 2023). "By examining the basal transcriptional programs present in senescing (Type V) and dying (Type D) tumor-derived cells, we determined that Type D and Type V cells have gene expression programs that resemble ASCL1 and NEUROD1 molecular subtypes of human SCLC, respectively." (PMID 37479684, 2023). "The expression of ASCL1 was lower in the NEC913 PDX tumor when compared to the original tumor." (PMID 35454817, 2022). "In neuronally committed NB cells, endogenous ASCL1 binds promoter, enhancer and super-enhancer regions, supporting proliferation and maintaining the mutually regulated core transcriptional circuit that is a signature of adrenergic-type neuroblastic tumours." (PMID 35366798, 2022). "In addition, key TFs related to SCLC tumor subtypes, such as ASCL1, NEUROD1, and POU2F3, were found to be differentially expressed in our cohort, as further described in the following sections." (PMID 36195615, 2022). "In all these tumours, manipulating ASCL1 activity could alter the balance between a proliferating progenitor tumour cell identity, usually associated with a poorer prognosis, and that of a more differentiated cell type where prognosis may be better." (PMID 35366798, 2022). "A subpopulation of GBM tumor mass cells expressing high levels of ASCL1 has been found." (PMID 35804976, 2022). "Interestingly, a recent study showed that proneural marker ASCL1 maintained the proneural phenotype of tumor cells by inhibiting the expression of mesenchymal marker NDRG1." (PMID 36061208, 2022). "Likewise, in the same cancer, an LSD1 inhibitor, ORY1001, favored Notch1 expression and suppressed tumor growth in vitro and in vivo through Notch-dependent ASCL1 repression." (PMID 34680255, 2021). "Each of these subtypes is defined by its inter tumor expression levels of the four key transcription regulators: Achaete–Scute Family BHLH Transcription Factor 1 (ASCL1), Neuronal Differentiation 1 (NEUROD1), POU Class 2 Homeobox 3 (POU2F3), and yes–associated protein 1 (YAP1)." (PMID 33809582, 2021).
tumor (continued). "Importantly, we demonstrated that netrin‐3 is also expressed in SCLC tumor cells, at least in part through the activities of ASCL1 and Neuro‐D1." (PMID 33719214, 2021). "This improvement in survival for the Ascl1CKO tumor mice also holds true even when analyzed by gender (not shown) and strongly suggests that it was due to the loss of ASCL1." (PMID 32573857, 2020). "Previously, we reported that ASCL1 is required for tumor formation in a mouse model of SCLC." (PMID 32573857, 2020). "Strikingly, we could block tumour formation completely by re-expressing Asense (homologue of human ASCL1), which we show is a direct target of Tailless." (PMID 32073402, 2020). "The aim of this study was to determine the protein expression levels of Notch1, Hes1,Ascl1, DLL3 in SCLC tumor specimen and the potential association of these biomarkersto platinum chemotherapy sensitivity, prognosis as well as clinical factors in SCLCpatients." (PMID 33104707, 2020). "Colocalization analysis revealed that 48% of ASCL1+ tumor cells were positive for the proliferation marker Ki67, whereas over 90% of ASCL1+ cells were OLIG2+ and SOX2+, indicating that these three transcription factors are coexpressed in the majority of the PDX‐GBM cells in vivo." (PMID 32573857, 2020). "The activation of doxycycline-inducible NOTCH1 and NOTCH3 in TT cells, through treatment with increased doses of doxycycline, has demonstrated a dose-dependent increase in NOTCH1, NOTCH3 and HES1 protein, a decrease in ASCL1 levels and ultimately a reduction in tumour growth in vitro and in vivo." (PMID 31443481, 2019). "In addition, we provide evidence that ASCL1-mediated pro-differentiation therapeutic strategies need to be carefully tuned and should take into consideration the nature of the tumor cell to differentiate." (PMID 30538287, 2019). "This inhibitor activates the NOTCH pathway, inhibiting, consequently, the transcription factor achaete–scute complex-like 1 (ASCL1), with this ultimately leading to tumorigenesis repression and to the reversion of the neuroendocrine phenotype in this type of tumour." (PMID 31443481, 2019). "Importantly, the CD133+ cell population isolated from SCLCs was markedly more capable of initiating tumors in nude mice than the CD133low/- cell population: ASCL1 was shown to be critical for the tumor-initiating capacity of CD133+ SCLCs." (PMID 30060526, 2018). "This expression may be a reflection of ASCL1 expression in the tumour cell of origin, as well as its functional role in neurogenesis." (PMID 29759978, 2018). "Other possible alternative modes of delivery include the use of functionalized Ascl1 protein, which could be delivered intracellularly, an approach that might be more useful when dealing with tumor masses." (PMID 28832532, 2017). "Importantly, forced Ascl1 expression attenuated tumor progression in intracranial xenografts, attesting to its potential in attenuating tumor growth in vivo." (PMID 28832532, 2017). "Next, we performed subcutaneous transplantations in mice to determine whether knocking down ASCL1 expression would suppress tumor growth or formation." (PMID 27462425, 2015). "Inverse relation of ASCL1 to DKK1 expression was observed for 15 out of 22 tumours (68%)." (PMID 19744316, 2009). "Additionally, ASCL1 influenced tumor immune dynamics and chemosensitivity in BC." (PMID 39963143, 2025). "Recent studies have revealed that OLIG2 and ASCL1 bind to each other’s genomic loci and downstream targets, cooperatively regulating tumor cell plasticity and heterogeneity, suggesting that transcription factor gene combinations—rather than individual factors—may drive tumor progression." (PMID 40428395, 2025). "However, in SCLC, the downregulation of ASCL1 may promote tumor cell proliferation and survival by inhibiting apoptotic pathways such as the caspase pathway." (PMID 40332288, 2025).
tumor (continued). "Therefore, high oxidative phosphorylation activity may display a key regulatory mechanism of tumor metabolic reprogramming, especially in ASCL1-driven SCLC." (PMID 40165271, 2025). "CU-PC01 tumours display DNPC-like clinicopathological features, including the absence of AR, PSA and PSMA, loss of PTEN and RB, and a lack of NE markers, including SYP, neuronal differentiation 1 (NEUROD1), POU class 2 homeobox 3 (POU2F3) and achaete-scute homolog 1 (ASCL1)." (PMID 38667288, 2024). "Interestingly, although both A and A2 scores were positively correlated with E scores for all cells in the tumor (sr=0.43 for A2; sr=0.09 for A), only A2 scores had a strong correlation with E scores for cells that express ASCL1 (sr=0.35 for A2; sr=−0.08 for A)." (PMID 36900269, 2023). "In the current study, using TMAs and specimen slides from a relatively large cohort (N = 192) of primary resected SCLC, we assessed the tumor‐derived protein expressions of ASCL1, NEUROD1, POU2F3, YAP1 as well as VIM, a mesenchymal marker which may be a potential assay to define SCLC‐I." (PMID 37789961, 2023). "Consequently, depletion of ASCL1 abolishes SCLC tumor growth both in vitro and in vivo." (PMID 35194152, 2022). "In addition, we found that ASCL1 was required for tumor initiation measured by tumor intake ratio." (PMID 35477723, 2022). "However, this endogenous level of expression must be tightly regulated as increasing ASCL1 leads to dramatic changes genome-wide and functionally results in a pronounced switch in tumour cell behaviour towards a less proliferative and more differentiated state." (PMID 35366798, 2022). "Notably, we could distinguish the clusters that correspond to the two tumor subtypes based on the differential accessibility to the ASCL1 and NEUROD1 promoters." (PMID 34599169, 2021). "Interestingly, the majority of cells within the tumor xenografts derived by ASCL1-transduced CSCs were small in size and focally organized as circular rosette structures around an eosinophilic neuropil core, thus strongly resembling typical neuronal differentiation." (PMID 30538287, 2019). "We hypothesize that miR-374a is up regulated in the field of cancerization, and in turn down regulates ASCL1 transcription factor, which may represent a reaction of epithelial cells to the presence of tumor in the lung; possibly counteracting and/or preventing tumor metastasis." (PMID 25705890, 2015). "To facilitate mechanistic and pharmacologic studies, we established NCI-LYM-1, a patient-derived organoid/PDX from an AR-negative, ASCL1+/SYP+ lymph node metastasis, which faithfully recapitulates the donor tumor’s molecular and phenotypic features." (PMID 41542660, 2026). "This follow-up study aimed to validate the unique metabolic phenotype in achaete-scute homologue 1 (ASCL1)-driven SCLC cell lines and human tumor tissue." (PMID 40165271, 2025). "In line with previous studies, 7 of the 14 ASCL1-positive cases were positively stained for both ASCL1 and NEUROD1 to varying degrees, and double-positive cells were distributed in part or the whole of the tumour area." (PMID 40595415, 2025). "For instance, up‐regulation of FGF9 significantly induces the expression of LUAD NE markers (e.g., ASCL1 and SYP), altering cell survival and proliferation characteristics, thus promoting tumour cell transformation." (PMID 40847555, 2025). "Another Elevated ASCL1 gene, CKB, has upregulated expression in both SCLC and ASCL1-high atypical teratoid/rhabdoid tumours, suggesting an ASCL1 interaction with oncogenic potential across various contexts." (PMID 40257984, 2025).
tumor (continued). "YAP1 expression emerges while ASCL1 and NEUROD1 expression decreases, resulting in a mixed tumour with some YAP1 and ASCL1 expressed side-by-side within the same tumour." (PMID 41290592, 2025). "Supporting the primary tumor analysis, we found that the FOXA2 locus was open in all 3 ASCL1+/FOXA2+ PDX tumors, but closed in the ASCL1+/FOXA2– PDX tumor." (PMID 40419484, 2025). "Eight genes were differentially expressed at both the mRNA and protein levels, with ASCL1, EDNRB, INSM1, SOX11, SOX4, SOX8, and SIX1 showing reduced expression in tumor tissues, and CTNNB1 showing increased expression compared with para-cancer tissues." (PMID 40771813, 2025). "Tumour cells with this genotype display a high level of plasticity, with an ASCL1-high/NEUROD1-low phenotype at early-stage disease and a NEUROD1-high/ASCL1-low phenotype in invasive late-stage tumours." (PMID 39567755, 2025). "In conclusion, integrating OTP and ASCL1 refines pulmonary NET classification into four histologically and biologically distinct subgroups, providing additional insight into tumor heterogeneity." (PMID 41196447, 2025). "In neuroendocrine cells, MYC activates Notch to dedifferentiate tumor cells, promoting a temporal shift in SCLC from ASCL1+ to NEUROD1+ to YAP1+ states." (PMID 40433367, 2025). "Daily oral administration of HOC in a nude mouse NEPC xenograft model markedly suppressed the tumor expression of EPHA3 and BRN2, along with their downstream effectors EZH2, ASCL1, and DLL3 and neuroendocrine markers SYP and CHGA." (PMID 41514539, 2025). "As with NEUROD1 and ASCL1 in their respective subtypes, ATOH1 supports cell viability in ATOH1 subtype tumor cells." (PMID 40305287, 2025). "The remaining 22 samples showed an intermingled expression pattern of ASCL1 and NEUROD1 in the same tumor areas." (PMID 40082639, 2025). "Several studies indicate that SOX2 influences the transitions between SCLC subtypes by modulating the expression of ASCL1 and NEUROD1, contributing to tumor heterogeneity." (PMID 41220942, 2025). "ASCL1 also plays a crucial role in determining NE cell fate, being highly expressed in classical SCLC and LCNEC tumours that maintain NE characteristics." (PMID 40847555, 2025). "Remarkably, when selecting only the tumour cells in the dataset, we also observed a similar expression pattern in NPC signature (based on SOX2, NES, and ASCL1 genes) and SSTR2, supporting the putative relationship between this NPC population and SSTR2 levels." (PMID 40268793, 2025). "While control tdTOM+ newly transformed tumor cells were mostly found adjacent to the SVZ and in the corpus callosum (arrows), Ascl1-OE GFP+ newly transformed tumor cells had migrated considerably into the striatum and upper cortical layers (arrows)." (PMID 39609428, 2024). "Subsequently, the binding of ASCL1 and OLIG2 to each other’s loci and to downstream target genes then determines the cell types and degree of migration of tumor cells." (PMID 39609428, 2024). "By 10 weeks, larger homogeneous clusters of ASCL1+;KRT8− tumor cells with NEPC histology were visible." (PMID 39394434, 2024). "ASCL1 is a known dependency in SCLC, likely a consequence of tumor initiation in pre-existing ASCL1+ NE cells." (PMID 39394434, 2024). "Transcription factors (TFs) like ASCL1 and OLIG2, which are co-expressed in GBMs (Module 8), play crucial roles in maintaining tumour cell heterogeneity and hierarchy." (PMID 39457550, 2024). "Our study indicates that genetic ablation of ASCL1 in NEPC organoids not only affected organoid and tumor growth as expected, but also restored Notch signaling and suppressed NE differentiation." (PMID 39024561, 2024). "This PARCB model generates two distinct tumor lineages characterized by either stem-like (POU2F3/ASCL2 subtype) or neuroendocrine features (ASCL1 subtype) that closely resemble the POU2F3 and ASCL1 subtypes seen in clinical SCNCs." (PMID 39589879, 2024).
tumor (continued). "In contrast, tumor cells with higher levels of OLIG2 relative to ASCL1, such as Ascl1-CKO tumors, favor activation of an OPC/oligodendrocyte program and a less diffuse tumor phenotype." (PMID 39609428, 2024). "ASCL1 inversely correlates with YAP1 signaling, and in GEMMs of SCLC, expression of constitutively active Yap1 resulted in tumor phenotype switching by upregulation of Notch2 and downstream Rest and Hes1." (PMID 39456533, 2024). "Treatment with iBAP-II repressed neuroendocrine lineage-specific ASCL1/MYCL/E2F signalling, decreasing cell viability and tumour growth." (PMID 39682746, 2024). "One study, however, showed that expression with ASCL1 is mutually exclusive, whereby NEPC PDX tumours either expressed one TF or the other." (PMID 39682746, 2024). "ASCL1, a marker of emerging NE cells, was detected at 4–6 weeks, appearing as EGFP+;KRT8+;ASCL1+ tumor cell clusters." (PMID 39394434, 2024). "These functions are consistent with the proposed roles for ASCL1 and OLIG2 as core regulators of tumor-propagating cells." (PMID 39609428, 2024). "To better determine the role of ASCL1 in regulating the hierarchy and heterogeneity of tumor cells in the GBM mouse model, we next performed scRNA-seq analyses of control and Ascl1-OE tumors." (PMID 39609428, 2024). "While the NE PDX models show a mutually exclusive expression of ASCL1 and NEUROD1, human NE tumors were found to exhibit a complex tumor structure with subtypes co-existing as separate sub-populations within the same tumor." (PMID 36711033, 2023). "Several transcription factors in small cell lung cancer (SCLC), including achaete-scute homolog 1 (ASCL1) and neurogenic differentiation factor 1 (NEUROD1), contribute to rapid tumor growth and early metastatic dissemination." (PMID 37253435, 2023). "ASCL1 is able to induce GBM stem cell differentiation, decrease proliferation rate, increase neurospheres formation in vitro, and tumor mass growth in vivo is inhibited when it is overexpressed." (PMID 35804976, 2022). "To estimate the limit of detection of ASCL1 and NEUROD1 signal in cfDNA, we applied the classifiers to serial dilutions of CDXs representing the three categories and found positive signals for ASCL1 and NEUROD1 down to 3% and 4% tumor fraction, respectively." (PMID 35941262, 2022). "Molecular studies using human SCLC (hSCLC) cell lines showed that ASCL1 and NEUROD1 are required for the survival of the cells’ increased tumor-initiating capacity in xenograft assays suggesting that these factors lead to similar cellular consequences." (PMID 36428693, 2022). "We then analyzed single-cell RNA-seq data from 2 paired human SCLCs before and after cisplatin recurrence where a subpopulation of ASCL1/INSM1-low, inflammatory-high tumor cells emerged after cisplatin recurrence." (PMID 36008402, 2022). "Thus, ASCL1 could be playing a greater role in progenitor maintenance or differentiation in NB cell lines depending on the developmental position of the cell of origin of the original tumour." (PMID 36263020, 2022). "These single-cell results confirmed the diversity of tumor cell states in SCLC tumors and the regulatory functions of ASCL1, NEUROD1 and other TFs that shape the states of malignant cells in SCLC patients." (PMID 36195615, 2022). "Compared with A375 cells, A375 xenograft tumor displayed an upregulation for glial and neuronal genes (GFAP, BDNF, MAP2, MTURN, ROBO2, SYT1 and TUBB3) and neural stemness genes (ASCL1, MSI1, PAX6, PDGFRA, SOX9, VIM, ZIC1/2)." (PMID 33468253, 2021). "The ASCL1 and NEUROD1 staining showed intra-tumoral heterogeneity that defined two separated tumor populations, which are present at different foci across the tumor section." (PMID 34599169, 2021). "We next performed double staining of ASCL1 and NEUROD1 by immunofluorescence (IF) in FLM3, to investigate potential coexpression in tumor cells, and observed that the vast majority of the cells showed an anticorrelated expression of the two TFs." (PMID 34599169, 2021).